RNU6-764P (RNA, U6 small nuclear 764, pseudogene)
Gene: Small nuclear RNA gene on chromosome X (152,250,572 to 152,250,676, reverse strand). Ensembl gene ENSG00000252205.
Homologues: Orthologues: chimpanzee U6 (100% identical), macaque U6 (96% identical), pig U6 (75% identical), dog RNU6-764P (70% identical), mouse Gm22139 (70% identical), mouse Gm23655 (65% identical), rabbit U6 (59% identical), rat LOC120099053 (56% identical). Paralogues in human: RNU6-1011P (74% identical), RNU6-1331P (74% identical), RNU6-263P (74% identical), RNU6-657P (74% identical), RNU6-723P (74% identical), RNU6-1151P (73% identical), RNU6-1158P (73% identical), RNU6-1257P (73% identical), RNU6-1263P (73% identical), RNU6-15P (73% identical), RNU6-21P (73% identical), RNU6-345P (73% identical), and 1286 more.